MTTP (microsomal triglyceride transfer protein)
Description:
Catalyzes the transport of triglyceride, cholesteryl ester, and phospholipid between phospholipid surfaces. Required for the assembly and secretion of plasma lipoproteins that contain apolipoprotein B. May be involved in regulating cholesteryl ester biosynthesis in cells that produce lipoproteins (By similarity).
Synonyms: MTP; ABL
Tractability: Small molecule: an approved drug acts on it; it belongs to a druggable protein family. Antibody: UniProt predicts a signal peptide or a membrane-spanning region. PROTAC: its protein half-life has been measured; a small molecule that binds it is known.
Target class: Other cytosolic protein
Chemical probes: CHEMBL356310, DIRLOTAPIDE
Safety:
Unwanted effects reported when the protein is acted on. In parentheses: how it was acted on, where the effect was seen, and who reports it.
Increased, Liver Steatosis (activation; source: AOP-Wiki)
Gene: Protein-coding gene on chromosome 4 (99,564,081 to 99,623,997, forward strand). Ensembl gene ENSG00000138823.
Subcellular location: Endoplasmic reticulum; Golgi apparatus
Subcellular location (Human Protein Atlas): Cytosol; Endoplasmic reticulum
Pathways (Reactome):
Transport of small molecules: Chylomicron assembly; LDL remodeling; VLDL assembly
Gene Ontology:
Molecular function: ceramide 1-phosphate transfer activity; cholesterol transfer activity; phosphatidylcholine transfer activity; phosphatidylethanolamine transfer activity; phospholipid transfer activity; protein binding; protein heterodimerization activity; triglyceride transfer activity; lipid transporter activity; apolipoprotein binding; lipid binding; protein-containing complex binding
Biological process: phospholipid transport; plasma lipoprotein particle assembly; protein secretion; triglyceride transport; cholesterol homeostasis; chylomicron assembly; lipid metabolic process; lipoprotein metabolic process; very-low-density lipoprotein particle assembly; ceramide 1-phosphate transport; circadian rhythm; intermembrane lipid transfer; lipid transport; response to calcium ion; sterol transport
Cellular component: endoplasmic reticulum; Golgi apparatus; receptor complex; basolateral plasma membrane; endoplasmic reticulum lumen; brush border membrane; microvillus membrane; vesicle
Genetic constraint (gnomAD): Loss-of-function variants: 48 observed, 90.92 expected, observed/expected ratio (o/e) 0.53, 90% interval 0.42 to 0.67. The upper end of that interval is the gene's LOEUF score, 0.67, which puts it in group 2 of 6, group 1 being the genes least tolerant of losing a copy. Missense variants: 905 observed, 1,080.2 expected, observed/expected ratio (o/e) 0.84, 90% interval 0.79 to 0.88. Synonymous variants: 336 observed, 391.65 expected, observed/expected ratio (o/e) 0.86, 90% interval 0.78 to 0.94.
Homologues: Orthologues: macaque MTTP (97% identical), chimpanzee MTTP (97% identical), rabbit MTTP (90% identical), pig MTTP (88% identical), dog MTTP (88% identical), rat Mttp (86% identical), mouse Mttp (86% identical), guinea pig MTTP (82% identical), tropical clawed frog mttp (62% identical), zebrafish mttp (54% identical), Drosophila melanogaster Mtp (22% identical), Caenorhabditis elegans dsc-4 (18% identical).
Diseases named in the same sentence as MTTP in open-access papers:
MTTP is named in the same sentence as 76 diseases in open-access papers, as found by Europe PMC text mining. Sharing a sentence is not in itself a finding about the gene and the disease. The quoted sentences say what the papers report.
Hepatic steatosis (39 papers, 2012 to 2025). Steatosis is a term used to denote lipid accumulation within hepatocytes. "Hepatic steatosis has been reported in subjects with mutations in MTTP, and pharmacologic inhibition or genetic deletion of MTTP caused hepatic steatosis." (PMID 36834959, 2023). "MTTP, which is involved in lipid metabolism, is affected by alcohol exposure and was reported to be associated with alcoholic fatty liver in the Korean population." (PMID 35864541, 2022). "Of concern, pharmacologic MTTP inhibition is associated with significant toxicities, including hepatic steatosis and increased liver aminotransferase levels." (PMID 32907986, 2020). "The increase in intestinal MTTP expression can be observed in high-cholesterol and HF diet-fed inositol-requiring enzyme 1 (IRE1β)-deficient mice, leading to hyperlipidemia and fatty liver." (PMID 30060615, 2018). "On the other hand, Koo (2013) has reviewed that hepatic steatosis can be observed in patients with ApoB100 mutation (hypobetalipoproteinemia) and MTTP mutation (abetalipoproteinemia)." (PMID 30060615, 2018). "Genetic defect in MTTP or APOB gene is associated with liver steatosis, obesity, and insulin resistance." (PMID 30037134, 2018). "In the host, genetic determinants of hepatic steatosis are observed, such as single-nucleotide polymorphisms (SNPs) in the microsomal triglyceride transfer protein (MTTP) gene." (PMID 28356060, 2017). "In the host, genetic determinants of hepatic steatosis are observed such as single-nucleotide polymorphisms (SNPs) in the microsomal triglyceride transfer protein (MTTP) gene and patatin-like phospholipase-3 (PNPLA3) gene." (PMID 28356060, 2017). "Hepatic steatosis was also associated with the GT/TT genotype of the MTTP -493G/T SNP in patients with chronic hepatitis C and HCV genotype 3." (PMID 28356060, 2017). "Hepatic steatosis was also associated with the TT/GT genotype of the MTTP -493G⁄T SNP in patients infected with HCV genotype 3 (P < 0.001)." (PMID 28356060, 2017). "Cases of MTTP gene mutation is characterized by abetalipoproteinemia and remarkable hepatic steatosis or cirrhosis." (PMID 26458397, 2015). "MTTP I128T is associated with a reduction in hepatic steatosis, plasma lipids, and apoB." (PMID 40507973, 2025). "Berberine has been proven to significantly reduce hepatic fat content in rats with NAFLD by decreasing methylation of the MTTP (microsomal triglyceride transfer protein) promoter and mitigating the hepatic steatosis caused by a high-fat dietary regimen in rodent models." (PMID 39065511, 2024). "•A rare MTTP variant, p.I564T, leads to progressive fatty liver disease and cirrhosis." (PMID 37484212, 2023). "•-493G/T and I128T polymorphisms in the MTTP gene are relevant in hepatic steatosis." (PMID 36027755, 2022). "Liver steatosis and fibrosis are more common in patients with low active genotype fatty liver, suggesting that MTTP gene polymorphism may affect the course of fatty liver." (PMID 35983527, 2022). "Conditional knockout of MTTP in hepatocytes caused moderate hepatic steatosis." (PMID 33168624, 2021). "Thus, while MTTP inhibition clearly lowers plasma lipids and increases hepatic lipids, it is unclear how this hepatic steatosis is associated with or dissociated from a metabolically deleterious phenotype." (PMID 32907986, 2020). "However, the promise of MTTP-targeted therapeutics has been questioned, as hepatic MTTP inhibition or MTTP deficiency induces hepatic steatosis and transaminitis." (PMID 32907986, 2020). "It was speculated that severe fatty liver may cause the decrease in ApoB100 and MTTP and reduce the liver secretion of VLDL-TG, leading to hepatic lipid accumulation." (PMID 30060615, 2018). "Abetalipoproteinemia (ABL) is a rare disease, characterized by absence or very low apoB-containing lipoproteins in plasma and remarkable hepatic steatosis or cirrhosis, which is attributable to decreased lipid secretion from the liver and caused by MTTP gene mutation." (PMID 26458397, 2015).
Hepatic steatosis (continued). "The aim of the present study was to determine whether the -493G/T (rs1800591), I128T (rs3816873), Q95H (rs61733139), and Q244E (rs17599091) Single Nucleotide Polymorphisms (SNPs) in the MTTP gene are linked to the presence of hepatic steatosis in patients with chronic hepatitis C." (PMID 36027755, 2022). "We assumed genetic effect of the MTTP polymorphisms may interact with the metabolic regulators, such as age, sex, body mass index (BMI), and insulin resistance, to regulate the lipid homeostasis and hepatic steatosis." (PMID 26458397, 2015). "The hepatic secretion of VLDL is restrained by the inhibition of microsomal triglyceride transfer protein (MTP; gene name, MTTP), leading to an increase in hepatic steatosis and a reduction in serum lipids and apoB." (PMID 40507973, 2025). "In the present study, the authors analyzed the effect of four candidate SNPs in the MTTP gene combined with host and viral characteristics on hepatic steatosis in a group of chronic hepatitis C patients." (PMID 36027755, 2022). "The present study showed that the viral genotype combined with the -493G/T and I128T SNPs in the MTTP gene influences hepatic steatosis." (PMID 36027755, 2022). "The association analysis of the group of patients with chronic hepatitis C provides useful information on the effect of HCV genotype 3 infections combined with the -493G/T and I128T SNPs in the MTTP gene on hepatic steatosis." (PMID 36027755, 2022). "Specific knockout of the MTTP gene in hepatocytes leads to the accumulation of a large amount lipids in mouse hepatocytes, and eventually results in hepatic steatosis and fatty liver." (PMID 36005631, 2022). "In summary, the present study highlighted the significant role of MTTP SNPs in the pathogenesis of hepatic steatosis in hepatitis C." (PMID 36027755, 2022). "In mice, the genetic deletion of liver MTTP induces hepatic fat accumulation; however, despite hepatic steatosis, these mice demonstrated normal hepatic insulin sensitivity." (PMID 32907986, 2020). "Moreover, inhibited SHP can prevent the development of hepatic steatosis by increasing hepatic very-low-density lipoprotein secretion and by increasing MTTP levels." (PMID 34357017, 2021). "Betaine, a lipotropic agent, has shown beneficial effects to revert HFD-induced hepatic steatosis acting on global methylome and, in detail, supports hypomethylation of CpG clusters in the microsomal triglyceride transfer protein (MTTP) promoter, which is involved in VLDL assembly and secretion." (PMID 32340286, 2020). "Apob mutant mice are quite phenotypically similar to MTTP-deficient mice, developing hepatic steatosis without a disruption in glucose or insulin tolerance." (PMID 32907986, 2020). "Thus, the decrease in MTTP and ApoB expression found in our study suggests the severe progression of fatty liver disease." (PMID 33187321, 2020). "Additionally, MTTP KO mice were also shown to be unable to produce VLDLs, manifesting lower plasma triglyceride levels and hepatic steatosis." (PMID 31491968, 2019). "Finally, the multivariable analysis determined the relationship between hepatic steatosis and different MTTP -493G/T SNP genotypes in the patients with HCV genotype 3." (PMID 28356060, 2017). "Microsomal triglyceride transfer protein (MTTP) deficient mice have reduced plasma triglycerides levels but develop hepatic steatosis without insulin resistance and inflammation." (PMID 23738334, 2013). "However, patients with abetalipoproteinemia also manifest hepatic steatosis because they also lack MTTP in hepatocytes." (PMID 23145105, 2012). "As in MTTP deficient mice, the TG levels are low as export does not function they show hepatic steatosis but lack insulin resistance or inflammation." (PMID 22363740, 2012). "Moreover, the overexpression of MTTP could reduce hepatic steatosis, inflammation, and fibrosis, implying that it may play an important role in the occurrence and development of HCC." (PMID 36838613, 2023).
Hepatic steatosis (continued). "Other studies have shown that inhibition of MTTP may lead to hepatic steatosis." (PMID 34184762, 2021). "Thus, MTTP deficiency does not alter hepatic or peripheral insulin action in young mice despite marked hepatic steatosis and increases in sn-1,2-DAGs in the lipid droplet fraction." (PMID 32907986, 2020). "In chronic hepatitis C patients infected with HCV genotype 3 and with the TT/GT genotype of the MTTP -493G/T SNP, a significant increase in hepatic steatosis was observed, which may indicate that this SNP has a significant influence on the accumulation of triglycerides in hepatocytes." (PMID 28356060, 2017). "Indeed, HCV replication relies on host lipid metabolism for its lifecycle and results in hepatic steatosis by several mechanisms such as enhancing lipogenesis, impairing mitochondrial lipid oxidation, and downregulating microsomal triglyceride transfer protein (MTTP) activity." (PMID 28883965, 2016). "In MTTP-knockout mice, there was a striking reduction in VLDL triglyceride accompanied by hepatic steatosis." (PMID 28953935, 2017). "Pathogenic variants were detected in the ABCB4 gene in a patient with idiopathic cholestasis, in the APOB and CP genes in a patient with hepatic steatosis, in the ABCB4 gene in a patient with elevated liver enzymes, and in the MTTP and AGL genes in a patient with cryptogenic cirrhosis." (PMID 40870862, 2025). "The Q95H and Q244E SNPs in the MTTP gene did not influence the presence of hepatic steatosis in this group of patients when combined with other variables." (PMID 36027755, 2022). "Considering the functional roles of MTTP in very-low-density lipoprotein (VLDL) assembly/secretion in hepatocytes, the diet-induced decreased expression of MTTP might promote liver steatosis through elevated formation of VLDL particles." (PMID 33777102, 2021). "Prior investigations have observed that MTTP knockout mice develop hepatic steatosis, with increased DAG and ceramide content but without the development of hepatic insulin resistance or glucose intolerance." (PMID 32907986, 2020). "MTTP and APOCIII are responsible for the assembly, formation, and release of VLDL from the hepatocytes and are regulated by the FOXOa1 and can contribute to hepatic steatosis, so we checked their gene expression and we saw a decreased level of both in the hepatocytes of the compound-treated group." (PMID 39759127, 2024). "However, the pathways involved in beta-oxidation and VLDL-export on hepatic steatosis were not changed significantly without changing the protein level of CPT-1 and MTTP." (PMID 29593573, 2018).
abetalipoproteinemia (33 papers, 2010 to 2025). "Abetalipoproteinemia is caused by mutations in MTTP—the gene encoding the microsomal triglyceride transfer protein." (PMID 39874248, 2025). "Genetic analysis revealed likely pathogenic compound heterozygous variants, c.59_61 + 14del and c.1946A > G (p.Asn649Ser), in the MTTP gene associated with abetalipoproteinemia." (PMID 40870862, 2025). "Mutations in MTTP lead to abetalipoproteinemia, a condition that disrupts fat and vitamin absorption." (PMID 39846623, 2025). "Rare variants in MTTP gene have been linked with susceptibility to MAFLD and rare and loss-of-function mutations in MTTP result in abetalipoproteinaemia." (PMID 38662298, 2024). "Although no CNVs were found for any genes on our candidate gene lists, a large deletion was found in the MTTP gene in a person with the phenotype of abetalipoproteinemia, and this is certainly the cause of his low HDL-C (22 mg/dl)." (PMID 35460704, 2022). "Loss-of-function mutations within MTTP result in severe autosomal recessive diseases, causing ataxia, failure to thrive, steatorrhea, and muscle weakness known as abetalipoproteinemia." (PMID 36685950, 2022). "Another type of treatable disease characterized by ataxia is Abetalipoproteinemia, which is caused by the mutation of the microsomal triglyceride transfer protein (MTTP)." (PMID 35933444, 2022). "Abetalipoproteinemia is provoked by mutations of both alleles of the microsomal triglyceride transfer protein (MTP) encoding gene." (PMID 33708142, 2021). "Abetalipoproteinemia (ABL) is a homozygous autosomal recessive disorder caused by mutations of the MTTP gene." (PMID 33584351, 2021). "The best examples of this are heterozygous truncating mutations in APOB [encoding apolipoprotein B (ApoB)], causing hypobetalipoproteinaemia and biallelic mutations in MTTP (encoding microsomal triglyceride transfer protein), which cause abetalipoproteinaemia." (PMID 27899914, 2016). "We discovered a novel mutation in MTTP gene and we confirmed the diagnosis of abetalipoproteinemia in new Tunisian families." (PMID 23556456, 2013). "Mutations introduced in either of the helices resulted in abolition of lipid binding, which provides an explanation for abetalipoproteinemia found in humans carrying point mutations in the MTTP gene." (PMID 20423497, 2010). "Also referred to as abetalipoproteinemia, this condition was first described by Bassen and Kornzweig in 1950 and is caused by pathogenic variants in the MTTP gene, which encodes the microsomal triglyceride transfer protein." (PMID 39846623, 2025). "Loss of function mutations in the MTTP gene results in abetalipoproteinemia." (PMID 35931202, 2022). "Our group studies evolution and structure function of MTP to identify different amino acids and structural motifs participating in the transfer of different lipids and to understand molecular bases for the missense mutations in the MTTP gene in abetalipoproteinemia patients." (PMID 35931202, 2022). "Its role as an essential chaperone for the biosynthesis of apolipoprotein B (apoB)-containing triglyceride-rich lipoproteins was established after the realization that abetalipoproteinemia patients carry mutations in the MTTP gene resulting in the loss of its lipid transfer activity." (PMID 22353470, 2012). "Abetalipoproteinemia (ABL) is a rare recessive condition caused by biallelicloss-of-function mutations in the MTTP gene encoding the microsomaltriglyceride transfer protein large subunit." (PMID 34078172, 2021). "Abetalipoproteinemia and homozygous hypobetalipoproteinemia are classical Mendelian autosomal recessive and co-dominant conditions, respectively, which are phenotypically similar and are usually caused by bi-allelic mutations in MTTP and APOB genes, respectively." (PMID 29540175, 2018).
abetalipoproteinemia (continued). "Abetalipoproteinemia (FHBL-SD1) and chylomicron retention disease (FHBL-SD3) are rare recessive disorders of lipoprotein metabolism due to mutations in MTTP and SAR1B genes, respectively, which lead to defective chylomicron formation and secretion." (PMID 36771214, 2023). "We have shown that TRF modifies clock genes and abetalipoproteinemia genes microsomal triglyceride transfer protein (MTTP) expression pattern." (PMID 32012883, 2020). "Investigation of genetic disorders, such as abetalipoproteinemia and hypobetalipoproteinemia, have been of immense support in defining the indispensable role of microsomal triglyceride transfer protein (MTTP) and Apo B-48 for the gut and Apo B-100 for the liver, respectively." (PMID 37558128, 2023). "Just recently, Hendriks’ group used this technique to knock out the APOB and MTTP genes in human fetal hepatocyte-derived organoids, deletions of which are responsible for two monogenic lipid disorders predisposing to NAFLD: familial hypolipoproteinemia and abetalipoproteinemia." (PMID 37175830, 2023). "Human microsomal triglyceride transfer protein (hMTP) plays an essential role in the assembly of apoB-containing lipoproteins, and has become an important drug target for the treatment of several disease states, such as abetalipoproteinemia, fat malabsorption and familial hypercholesterolemia." (PMID 34206252, 2021). "Human mutations in the MTTP gene that prevent lipid transfer and APOB secretion cause the disease abetalipoproteinemia (OMIM 200100), characterized by a virtual absence of plasma B-lps." (PMID 32760060, 2020). "Unlike homozygous embryos in abetalipoproteinemia and hypobetalipoproteinemia (with ApoB and MTTP deletions, respectively), which developed malformations leading to embryo resorption, homozygous Sar1bdel/del and Sar1bmut/mut embryos revealed no macroscopic abnormalities at E18.5." (PMID 37558128, 2023).